ANGPTL4 (angiopoietin like 4)
Diseases named in the same sentence as ANGPTL4 in open-access papers (continued):
Sharing a sentence is not in itself a finding about the gene and the disease.
breast tumors (17 papers, 2012 to 2025). "Consistently, TGF-β, which upregulates ANGPTL4 in breast tumor cells, caused enhanced vascular leakiness and promoted the transendothelial migration of breast tumor cells to the lung." (PMID 22481923, 2012). "We find that phosphorylated FMNL2 drives TGFβ‐induced invasion of breast tumor cells by critically promoting secretion of the pro‐metastatic factor ANGPTL4." (PMID 36691769, 2023). "TGF-β upregulated ANGPTL4 in breast tumor cells and then disrupted the endothelial cell–cell junctions, leading to enhanced vascular leakiness and transendothelial migration of the tumor cells." (PMID 23925665, 2013). "In addition, TGF-β signaling primes breast tumors for lung metastasis seeding and brain metastasis by inducing ANGPTL4 expression." (PMID 38643448, 2024). "Interestingly, previous studies showed that the induction of angiopoetin like-4 (ANGPTL4), a member of angiopoietins, increased extravasation of breast tumor cells in the lung." (PMID 32082485, 2020). "In addition, a previous study was reported that TGF-β could prime breast tumors for lung metastasis through ANGPTL4." (PMID 28903395, 2017). "It was showed that ANGPTL4 and KLF4 showed significantly higher expression levels in breast tumor tissues compared to adjacent normal tissues." (PMID 40616161, 2025). "To investigate whether lipid-enriched adipocytes play a role in activating ANGPTL4 in TNBC cells, we assessed the bidirectional lipid transfer between breast tumors and surrounding adipocytes." (PMID 40616161, 2025).
diabetic nephropathy (17 papers, 2014 to 2026). "Future research should continue to explore the specific mechanisms of ANGPTL4 in diabetic kidney disease and develop ANGPTL4-based diagnostic and therapeutic strategies to provide more effective treatment options for DKD patients." (PMID 39840089, 2024). "In this study, we examined levels of circulating ANGPTL4 in people with diabetic nephropathy (DN) and its association with established DN-associated proteins such as IGFBP1 and IGFBP4." (PMID 31772941, 2019). "ANGPTL4 and ANGPTL8, which regulate lipid metabolism and inflammatory responses, have been associated with both diabetic nephropathy and retinopathy." (PMID 40137149, 2025). "Subsequent studies have consistently revealed increased expression of ANGPTL4 in various renal pathologies, including diabetic nephropathy (DN), IgA nephropathy, and MN, which is consistent with our findings 21, 35-39." (PMID 39776814, 2025). "Human studies have shown a positive correlation between Angptl4 levels and expression of characteristics of diabetic nephropathy." (PMID 39630889, 2024). "The upregulation of Angptl4 was found in the development of diabetic nephropathy, indicating a potential role for Angptl4 in DN for the detection of a diabetic kidney disease and as a therapeutic target." (PMID 37853335, 2023). "The association of urinary levels of ANGPTL-4 and KIM-1 with UACR and eGFR and significant prevalence in the diabetic kidney disease population illustrates the diagnostic potential of these biomarkers." (PMID 37108963, 2023). "Upregulation of Angptl4 in diabetic nephropathy was proposed to contribute to the development of diabetic nephropathy, indicating a potential role of Angptl4 for the detection of a diabetic kidney disease and as a potential therapeutic target." (PMID 37853335, 2023). "The urinary levels of ANGPTL-4 and KIM-1 were significantly associated with diabetic kidney disease even after adjustments were made for demographic, clinical, and laboratory parameters." (PMID 37108963, 2023). "Increased glomerular and urinary ANGPTL4 expression has been identified in diabetic rats, and hyposialylated ANGPTL4 induces apoptosis of podocytes via β1 Integrin/FAK signaling in diabetic nephropathy." (PMID 34616362, 2021). "ANGPTL4 is considered as a biochemical marker for the detection of a diabetic kidney disease in patients with T2D." (PMID 34876931, 2021). "Renal expression of several genes, such as Angptl4, Spon2 (Mindin), Pappa and Txnip, which have been shown to be upregulated in diabetic nephropathy, was found to be increased under hyperglycemic conditions." (PMID 33923831, 2021). "This study aimed to investigate the effects of benazepril hydrochloride (BH) on proteinuria and ANGPTL-4 expression in a diabetic nephropathy (DN) rat model." (PMID 28978304, 2017). "Subsequent studies show the existence of high pI hyposialylated Angptl4 in glomeruli of rats with diabetic nephropathy, and treatment of Zucker Diabetic Fatty rats with ManNAc resulted in a significant decline in proteinuria." (PMID 24611049, 2014). "There is an association between Angptl4 and diabetic kidney disease; however, this association has not been well investigated." (PMID 39630889, 2024). "The study findings suggest that a combination of ANGPTL-4 and KIM-1 may strengthen the diagnostic approach to diabetic kidney disease." (PMID 37108963, 2023). "This was further confirmed by the multivariate analysis in which ANGPTL-4 was found to be significantly prevalent in a diabetic kidney disease population even after adjustments were made for potential confounders, including duration of T2DM, HbA1c, BUN, and eGFR." (PMID 37108963, 2023). "Importantly, targeting renal ANGPTL4 with antisense oligonucleotides (ASOs) has shown promising protective effects against fibrosis in diabetic kidneys, paving the way for innovative therapeutic strategies to combat diabetic kidney disease and other fibrotic disorders." (PMID 42064807, 2026).
diabetic nephropathy (continued). "ANGPTLs, particularly ANGPTL3, ANGPTL4, and ANGPTL8, play pivotal roles in regulating lipid metabolism and energy homeostasis, with emerging implications for diabetic nephropathy." (PMID 38790911, 2024). "In individuals with diabetic nephropathy, our data presents a notable rise in the levels of circulating Ang2, ANGPTL8, and ANGPTL4." (PMID 38790911, 2024). "Altogether, this suggests a potential role for ANGPTL4 in DN perhaps through its role in inhibiting LPL activity and promotes ANGPTL4 as a biochemical marker for the detection of a diabetic kidney disease in patients with T2D." (PMID 31772941, 2019). "Conversion of this high pI hyposialylated Angptl4 to sialylated neutral pI Angptl4 in vivo using the sialic acid precursor N-acetyl-D-mannosamine (ManNAc) reduces proteinuria, and this improvement in proteinuria was noted in rats with MCD and diabetic nephropathy." (PMID 24611049, 2014). "The Ang2 levels increased in conjunction with higher levels of ANGPTL8 and ANGPTL4 and the ACR but showed a negative relationship with the eGFR and systolic blood pressure, suggesting possible involvement in diabetic nephropathy." (PMID 38790911, 2024).
Glucose intolerance (17 papers, 2008 to 2025). Glucose intolerance (GI) can be defined as dysglycemia that comprises both prediabetes and diabetes. "In multivariable models, glucose intolerance was independently associated with serum ANGPTL4 concentrations, suggesting a potential physiological link between ANGPTL4 and glucose metabolism that warrants further investigation." (PMID 41226996, 2025). "Genetic studies in humans have revealed a positive association between ANGPTL4 and glucose intolerance." (PMID 37185283, 2023). "Particularly, ANGPTL4 loss, although it leads to an increment of visceral adipose tissue mass, also raises plasma insulin levels and reduces glucose intolerance via a mechanism that is at least partly dependent on the gut microbiota." (PMID 30944669, 2019). "Together, our results indicate that loss of ANGPTL4 uncouples visceral obesity from glucose intolerance partly via the gut microbiota." (PMID 29502266, 2018). "Notably, in a study evaluating the role of angiopoietin-like 4 (ANGPTL4) in metabolic dysfunction, the loss of the expression of this adipokine uncoupled visceral fat accumulation from glucose intolerance via the gut microbiota." (PMID 35634505, 2022). "In our study, serum ANGPTL4 concentrations were significantly higher in individuals with glucose intolerance." (PMID 41226996, 2025). "In ROC analyses, serum ANGPTL4 discriminated glucose intolerance with an AUC of 0.838 (95% CI, 0.797–0.879)." (PMID 41226996, 2025). "In diabetic mice, ANGPTL4 treatment decreased glucose to a normal level, and significantly improved glucose intolerance." (PMID 38140923, 2023). "In routine health check-up settings, measurement of serum ANGPTL4 may, pending external validation, serve as a complementary screening aid to identify individuals with possible glucose intolerance, given its practical convenience in clinical workflows." (PMID 41226996, 2025). "One possible mechanism is that glucose intolerance is often accompanied by elevated plasma free fatty acids and ANGPTL4 expression in multiple tissues, including liver and adipose tissue, thought to be primarily regulated by peroxisome proliferator-activated receptors (PPARs)." (PMID 41226996, 2025).
lung adenocarcinoma (17 papers, 2010 to 2026). A carcinoma that arises from the lung and is characterized by the presence of malignant glandular epithelial cells. "Elevated expression of ANGPTL4 has been observed in lung adenocarcinoma, and its expression is significantly correlated with poor prognosis." (PMID 41562084, 2025). "By examining the characteristics of gefitinib-resistant PC9/GR cells in nonsmall cell lung cancer cells, we investigated the function and mechanism of ANGPTL4 in the process of acquiring drug resistance in lung adenocarcinoma in the current study." (PMID 36467503, 2022). "This suggests that ANGPTL4 regulates gefitinib resistance in lung adenocarcinoma cells through the NLRP3/ASC/Caspase8 pathway." (PMID 36467503, 2022). "Collectively, ANGPTL4 inhibits lung adenocarcinoma cell pyroptosis and apoptosis by regulating the NLRP3\ASC\Caspase 8 pathway both in vivo and in vitro." (PMID 36467503, 2022). "And ANGPTL4 participates in the construction of GRG signature in lung adenocarcinoma to predict the survival and metastasis of patients." (PMID 33228592, 2020). "With the increasing risk score of patients with lymph node metastasis of lung adenocarcinoma, the expression of high-risk mRNAs (HMMR, B4GALT1, ANGPTL4, EXT1, GPC1, RBCK1, SOD1, AGRN) was obviously upregulated." (PMID 31847905, 2019). "In addition, ANGPTL4 expression was higher in lung adenocarcinoma (LUAD) samples, a subtype of NSCLC, than in normal lung counterparts." (PMID 41347893, 2026). "ANGPTL4 may be an effective new target for inhibiting EGFR-TKI resistance in lung adenocarcinoma cells." (PMID 36467503, 2022). "The results confirm that ANGPTL4 promotes the development of resistance to EGFR-TKIs in lung adenocarcinoma cells and that ANGPTL4 may be a potential target for overcoming resistance to EGFR-TKIs." (PMID 36467503, 2022). "In our previous study, we found high expression of ANGPTL4 in PC9/GR cells, suggesting that ANGPTL4 may be one of the potential targets for gefitinib resistance in lung adenocarcinoma cells." (PMID 36467503, 2022). "In addition, ANGPTL4 is significantly related to the poor prognosis of patients with non-small-cell lung cancer, lung adenocarcinoma, and cervical cancer." (PMID 34950205, 2021). "However, to the best of our knowledge, there have been no studies on the mechanism of acquired EGFR-TKI resistance in relation to ANGPTL4 in lung adenocarcinoma cells, and it remains unknown whether ANGPTL4 is involved in EGFR-TKI resistance." (PMID 36467503, 2022). "We identified four biomarkers (MAP3K8, CCL20, VEGFC, and ANGPTL4) that could predict overall survival in lung adenocarcinoma (HR = 1.98, 95% CI 1.48 to 2.64, P = 4.19e−06) and this model could be used as a classifier for the evaluation of low-risk and high-risk groups." (PMID 32019546, 2020). "ANGPTL4 has been shown to promote lung adenocarcinoma (LUAD) cell proliferation, migration invasion, and lipid production; conversely, knockdown of ANGPTL4 inhibited migration and apoptosis." (PMID 40723247, 2025). "ANGPTL4 inhibited pyroptosis and apoptosis by regulating the NLRP3/ASC/Caspase 8 pathway, leading to resistance to gefitinib in lung adenocarcinoma." (PMID 36467503, 2022).
Hypertension (16 papers, 2013 to 2024). The presence of chronic increased pressure in the systemic arterial system. "This study indicates that ANGPTL4 has potential clinical value for AF associated with hypertension and other disorders." (PMID 34422410, 2021). "We later demonstrated increased circulating levels of ANGPTL8 and ANGPTL4 in adults with hypertension." (PMID 38189043, 2023). "Here, we found the significant association of ADM, EDN1, ANGPTL4, USP8, NFIL3, MSR1, and CEBPD genes with hypertension." (PMID 35205232, 2022). "There were more elderly individuals (55% vs. 36%, P < 0.01) and more patients with hypertension (65% vs. 53%, P < 0.05) in the ANGPTL4 < 497.5 ng/mL group than that in the ANGPTL4 > 497.5 ng/mL group." (PMID 34742313, 2021). "Consistently, circulating ANGPTL4 protein levels are significantly up-regulated in patients with hypertension." (PMID 33593372, 2021). "There were lower levels of ANGPTL4 in the hypertension group (541.78 ± 453.35 vs. 659.54 ± 799.80 ng/mL, P < 0.05) and the old-aged group (541.10 ± 717.23 vs. 632.02 ± 504.20 ng/mL, P < 0.05) than in their control groups." (PMID 34742313, 2021). "HDL-C-associated ANGPTL4 p.E40K appears to decrease risk of T2D, CAD, and hypertension but is also associated with an increased risk of ankylosing spondylitis, hence a potential complication of targeting this gene." (PMID 33339817, 2020). "Considering these data, the increased levels of ANGPTL4 in both plasma and adipose tissues of subjects with hypertension in our study support that this protein may participate in hypertension development in this population." (PMID 29490644, 2018). "Therefore, the effect of hypertension on ANGPTL-4 should be investigated in further studies." (PMID 28978304, 2017). "From 50 DEGs, we ranked 7 hypertension-related genes (p-value < 0.05): ADM, ANGPTL4, USP8, EDN, NFIL3, MSR1, and CEBPD." (PMID 35205232, 2022). "ADM, EDN1, ANGPTL4, NFIL3, MSR1, CEBPD, and USP8, based on their FDR values (<0.05, p-values (≤0.05)), were the top DEGs for hypertension." (PMID 35205232, 2022). "The gene expression of ANGPTL4 and ANGPTL8 in adipose tissues displayed a similar pattern as the circulating levels in that their expression was elevated in subjects with hypertension." (PMID 29490644, 2018). "In conclusion, our data illustrate that ANGPTL4 and ANGPTL8 levels in both plasma and adipose tissues are increased in subjects with hypertension." (PMID 29490644, 2018). "In conclusion, ANGPTL4 and ANGPTL8 levels are increased in both plasma and adipose tissues of subjects with hypertension." (PMID 29490644, 2018). "The elevated levels of ANGPTL4 and ANGPTL8 in hypertensive subjects highlight their potential involvement, their potential role as biomarkers for hypertension and their therapeutic value in hypertension given their roles in regulating lipid metabolism." (PMID 29490644, 2018). "Subsequently, the independent association between FABP4, ANGPTL3 and ANGPTL4, and CAD was assessed in various subgroups according to sex (male or female) and hypertension (with or without)." (PMID 38425231, 2024). "Given the role of ANGPTL3, ANGPTL4 and ANGPTL8 in regulating lipid metabolism we hypothesised that their levels might be increased in subjects with hypertension." (PMID 29490644, 2018). "Dyslipidaemia is a risk factor for hypertension development; however, the roles of ANGPTL3, ANGPTL4 and ANGPTL8 in subjects with hypertension have not yet been established." (PMID 29490644, 2018). "Serum ANGPTL4 and ANGPTL8 levels are increased in patients with hypertension." (PMID 29940978, 2018). "Because this study was focused on the effects of BH on DN, blood pressure was not measured and the influence of hypertension on ANGPTL-4 was not considered." (PMID 28978304, 2017).
Hypertension (continued). "More importantly, multiple regression analysis revealed that the association between ANGPTL4 and SUA level was independent of age, gender, statin, BMI, hypertension, and eGFR as well as serum hs-CRP levels, indicating that SUA is a potential contributor to ANGPTL4." (PMID 35711366, 2022). "The circulating levels of ANGPTL4 and ANGPTL8 were increased in subjects with hypertension compared to those in subjects without hypertension in both the entire study population and the T2D subgroup." (PMID 29490644, 2018). "Conversely, ANGPTL4 and ANGPTL8 levels were elevated by 1.6- and 3-fold, respectively, in subjects with hypertension compared to those in subjects without hypertension (both p < 0.05)." (PMID 29490644, 2018). "In this study, we measured the expression of ANGPTL3, ANGPTL4 and ANGPTL8 in both plasma and adipose tissue in subjects with and without hypertension." (PMID 29490644, 2018). "This study compared the plasma and adipose tissue levels of ANGPTL3, ANGPTL4 and ANGPTL8 in age- and body mass index-matched subjects with and without hypertension." (PMID 29490644, 2018). "ANGPTL4 and LIPG PTV carriers in turn had lower risks of hypertension compared to noncarriers." (PMID 33909604, 2021). "Similarly, in subjects with T2D, ANGPTL4 and ANGPTL8 levels (p < 0.05), but not ANGPTL3 levels, were significantly higher in subjects with hypertension." (PMID 29490644, 2018). "Therefore, we examined the plasma and adipose tissue levels of ANGPTL3, ANGPTL4 and ANGPTL8 in subjects with or without hypertension using ELISA and real-time PCR." (PMID 29490644, 2018). "Similarly, ANGPTL4 and ANGPTL8 levels were also elevated in subjects with T2D and hypertension than in those with T2D but not hypertension." (PMID 29490644, 2018).